RAD52 (RAD52 DNA repair protein)
Diseases named in the same sentence as RAD52 in open-access papers (continued):
Sharing a sentence is not in itself a finding about the gene and the disease.
cancer (103 papers, 2012 to 2026). A tumor composed of atypical neoplastic, often pleomorphic cells that invade other tissues. "Human RAD52 is a prime target for synthetic lethality approaches to treat cancers with deficiency in homologous recombination." (PMID 41603734, 2026). "The correlation between specific RAD52 genetic variants and cancer development has also been established in several studies." (PMID 36980703, 2023). "Previous studies suggested that RAD52 is essential for the survival of BRCA1/2 deficient cancer cells, suggesting that a RAD52-dependent repair pathway is indispensable in BRCA1/2-deficient cells." (PMID 37777505, 2023). "This further strengthens a role for FAAP20 in HR as loss of other HR factors are also shown to cause sensitivity to RAD52 inhibition (RAD52i) in cancer cells." (PMID 37620397, 2023). "In this report we did a pan-cancer analysis using data reported on the Catalogue of Somatic Mutations in Cancers (COSMIC) to identify double mutants between RAD52 and BRCA1, BRCA2 or PALB2 that occur in cancer cells." (PMID 36107942, 2022). "Since FANCJ is a tumor suppressor and is associated with a broad range of cancers, inhibition of RAD52 in combination with G4-stabilizing drugs provides new strategies for targeted cancer treatment of FANCJ-deficient tumors." (PMID 36470428, 2022). "That is changing now, as recent work has shown RAD52 to be critical for backup DNA repair pathways in HR-deficient cancer cells." (PMID 34887904, 2021). "Studies on the impact of variability of the RAD52 gene supplement the functional assessment of the role of RAD52 inhibition in killing BRCA-deficient cancer." (PMID 33671579, 2021). "These new findings make RAD52 an attractive target for the development of anti-cancer therapies against BRCA-deficient cancers." (PMID 34887904, 2021). "But the most remarkable pro-cancer RAD52 phenotype is seen in cancer cells deficient in any of the following DNA repair proteins: BRCA1, BRCA2, PALB2, XAB2 or RAD51 paralogs: RAD51B, RAD51C, RAD51D, XRCC2 and XRCC3." (PMID 34887904, 2021). "The contributions of RAD52 that are essential to the viability of HR-deficient cancer cells are currently under investigation." (PMID 34887904, 2021). "Small-molecule RAD52 inhibitors are discovered by structure-based selection and proposed to be suitable for disruption of RAD52 rings in BRCA-deficient cancers." (PMID 34201502, 2021). "The synthetic lethality between RAD52 and BRCA1/2 has long been established, identifying RAD52 as a potential therapeutic target against cancers with BRCA1/2 gene mutations." (PMID 33995041, 2021). "Later, our and several other groups developed small molecule RAD52 inhibitors to specifically suppress the growth of BRCA-deficient cancer cells." (PMID 34887904, 2021). "In terms of the HR pathway, RAD52 has been proposed as another target to sensitize BRCA-deficient cancer cells." (PMID 33922657, 2021). "While PARP inhibitors increase the DNA damage load for the HR pathway and inhibit alternative a-EJ pathway, RAD52 inhibitors block the escape route for BRCA-deficient cancer cells through RAD52-dependent mechanism(s) of DNA repair." (PMID 34887904, 2021). "Another BIR-like mechanism, namely, alternative lengthening of telomeres (ALT) is implicated as a RAD52-dependent process involved in the development of human cancers." (PMID 34887904, 2021). "This differential effect renders RAD52 as a potential therapeutic target to treat cancers with such mutations." (PMID 33995041, 2021). "We were curious to see if RPA:RAD52 PPI inhibitors would show synthetic lethality in HR-deficient cancer cell lines, so we examined the cytotoxicity of quinacrine, mitoxantrone, and doxorubicin in cells with impaired BRCA1 or BRCA2 function." (PMID 33784323, 2021). "In this study, we revealed that curcumin is a potential RAD52 inhibitor that increases DNA damage sensitivity in BRCA2-deficient cancer." (PMID 33922657, 2021).
cancer (continued). "A couple of studies have investigated the effect of treating BRCA-deficient cancer cells with RAD52 inhibitors discovered through various strategies." (PMID 33995041, 2021). "Here, we exploited a series of computational and biochemical assays to discover and characterize specific RAD52 inhibitors inducing synthetic lethality in BRCA2-mutated cancer cells." (PMID 33995041, 2021). "Inactivation of RAD52 is synthetically lethal to homologous recombination (HR) deficient cancer cell lines." (PMID 33784323, 2021). "The impact of RAD52 inhibition on tumor suppression needs to be further validated before inhibitors can be tested for cancer prevention in BRCA1/2 mutation carriers." (PMID 32255263, 2020). "Previous studies have shown that RAD52 is required for viability of BRCA1- and BRCA2-deficient cells, suggesting a targeted treatment opportunity via inhibition of RAD52 to specifically kill cancer cells with BRCA deficiency." (PMID 31569559, 2019). "Since DNA repair protein RAD52 has previously been implicated in the development of resistance to cancer therapy 22, RDM1 was initially indicated to have a similar function to RAD52 in DNA repair pathways." (PMID 30868057, 2019). "RAD52 maintains residual HR in BRCA-deficient PARPi-treated cancer cells, so simultaneous targeting PARP1 and RAD52 represents an attractive therapeutic approach." (PMID 31615159, 2019). "Evidence suggests that variations in RAD52 expression can influence HR activity and, subsequently, influence the predisposition and treatment efficacy of cancer." (PMID 31652722, 2019). "New approaches of RAD52 inhibition would potentially provide a complementary strategy for targeting BRCA-deficient cancers in addition to PARP inhibitors." (PMID 31652722, 2019). "The mechanism by which RAD52 depletion causes synthetic lethality in BRCA1 mutant cancer cells depends on the 5′ endonuclease EEPD1, which normally functions to cleave stressed replication forks to initiate HR repair." (PMID 29145865, 2017). "Targeting human RAD52 represents a selective therapeutic approach for BRCA2-deficient cancers due to the synthetic lethality of RAD52 and BRCA2." (PMID 29215575, 2017). "Depletion of RAD52 results in synthetic lethality of these homologous recombination (HR)-deficient cancers." (PMID 29145865, 2017). "Since BRCA1/2 mutant cancer cells use RAD52 as an escape pathway for HR-mediated replication fork repair and restart, depleting RAD52 causes mitotic catastrophe and synthetic lethality in these cells." (PMID 29145865, 2017). "The BRCA-deficient cancer cells can still survive, but become “addicted” to other DNA repair proteins – among them a protein called RAD52." (PMID 27434671, 2016). "Conversely, there was an under-representation of RAD52 rs1051669 AA genotype (alone associated with an increased risk to develop cancer) in carriers of the variant C allele of rs2155209." (PMID 26735576, 2016). "Conversely, the variant genotype AA of RAD52 rs1051669 was associated with increased risk of cancer (OR 1.68, 95% CI 1.11–2.54, p = 0.01)." (PMID 26735576, 2016). "Recent studies have highlighted importance of RAD52 in human cancer cell lines deficient in BRCA1, PALB2 or BRCA2, as its depletion led to cell death in a synthetic lethality manner." (PMID 26610585, 2015). "However, in human cancers, high expression levels of RAD52 have been observed and are associated with poor survival outcome." (PMID 38658755, 2024). "Thus, we suggest that evaluating ERCC6L levels and mutations in cancer should be investigated as a potential biomarker for response to targeting RAD52, and vice versa." (PMID 39561207, 2024). "Therefore, cell viability and RAD52 foci formation in BRCA1/2-deficient cancer cells are often performed to indirectly demonstrate target engagement and synthetic lethality." (PMID 36980703, 2023). "Furthermore, inhibiting RAD52 in cancer cells harboring BRCA2 mutations can selectively and effectively kill cells." (PMID 36107942, 2022).
cancer (continued). "Altogether, defects in SSA underlined by RAD52 p.S346X variant might be associated with a reduced cancer risk in BRCA2-mutation carriers." (PMID 33671579, 2021). "Pharmacologically inhibiting RAD52 specifically eradicates BRCA-deficient cancer cells." (PMID 33922657, 2021). "They concluded that RAD52 inhibitors might increase the efficacy of PARP inhibitors-based treatment of cancers with BRCA-deficiency by the triggering dual synthetic lethality." (PMID 33671579, 2021). "The main conclusion from our model is that DSS1-RAD52 interaction could allow rescue for BRCA2-deficiency in cancer cells by promoting RAD52-mediated activities via SSA and BIR pathways." (PMID 31799622, 2020). "Interestingly, loss of RAD52 has been shown to reduces cancer predisposition and increases the lifespan of adenomatous polyposis coli (APC)- or ataxia-telangiectasia mutated (ATM)-deficient animals." (PMID 32355220, 2020). "As the Rad51 and Rad52 protein sequences are highly conserved in human and S. cerevisiae, the functional impact of rare cancer-associated missense variants in both HR repair genes was evaluated by constructing yeast strains carrying correspondent mutated alleles." (PMID 32656256, 2020). "Alternatively, it is possible that cells undergoing loss of heterozygosity in BRCA2 mutation carriers undergo apoptosis in the presence of RAD52 S346X variant, due to the persistence of unrepaired DSBs that may suppress tumorigenesis and reduce cancer risk." (PMID 32255263, 2020). "The risk assessment of BRCA1/2 mutation carriers inheriting other RAD52 variants that disrupt the protein function may also identify other alleles that are associated with reduced cancer risk." (PMID 32255263, 2020). "However, cancer cells that are deficient in BRCA substitute its activity with RAD52, which, thanks to its ssDNA and RAD51-binding sites, is able to manage HR in a BRCA-independent manner." (PMID 31615159, 2019). "These various functions of RAD52 to deal with replication stress have been linked to the protection of genome stability at common fragile sites, which are often associated with the DNA breakpoints in cancer." (PMID 31569559, 2019). "So, the correlation between genetic variants in DDR genes, such as RAD52, and protein expression could help to predict clinical outcome, treatment resistance, and monitor carcinogenesis in cancer patients." (PMID 31652722, 2019). "A deeper understanding of the context-specific roles of RAD52 will allow for the identification of new paradigms in which RAD52 targeting may control tumor growth, even outside the realm of HR-deficient cancers." (PMID 31340507, 2019). "Depleting RAD52 can cause synthetic lethality in BRCA1/2 mutant cancers by an unknown molecular mechanism." (PMID 29145865, 2017). "We then investigated whether aNHEJ was the escape pathway utilized by the EEPD1/RAD52 co-depleted BRCA1-deficient cancer cells for survival." (PMID 29145865, 2017). "Although it is clear that RAD52 is important for survival and uncontrolled proliferation of BRCA-deficient cancer cells, the molecular mechanism by which RAD52 allows BRCA-deficient cells to survive is unknown." (PMID 27434671, 2016). "The Skorski’s group targeted RAD52 in BRCA-deficient cancer cells using a small peptide aptamer." (PMID 27649245, 2016). "However, how Rad52 activity helps HR-deficient cancers to survive is unclear." (PMID 36010882, 2022). "Targeting RAD52 could be a potential personalized therapy for BRCA2-deficient cancer." (PMID 33922657, 2021). "The results indicate that the RPA:RAD52 PPI could be a therapeutic target for HR-deficient cancers." (PMID 33784323, 2021). "Recently, RAD52, a repair protein involved in numerous pathways, has become a promising cancer drug target." (PMID 40184180, 2025).
cancer (continued). "We believe that our current findings using a minimal system contribute to a better understanding of the single-strand annealing mechanism by RAD52 and will help to develop drugs that efficiently target it for cancer treatments." (PMID 40184180, 2025). "Only ten years ago, when RAD52 depletion was observed to induce synthetic lethality in BRCA2, BRCA1, and PALB2 mutated cancer cells, its potential for anticancer therapy development began to be understood." (PMID 39112549, 2024). "With this in mind, several RAD52 inhibitors have been developed and show promising results in killing BRCA2-deficient cancer cells." (PMID 38658755, 2024). "Mammalian RAD52 is a protein that protects DNA integrity through its roles in DNA repair and replication, and is being developed as a target for cancer treatment." (PMID 39561207, 2024). "In cancer cells deficient in the BRCA2 complex, the alternative HR pathway involving RAD52 must step up to continue HR, but most importantly, it must continue to repair the broken DNA." (PMID 38397158, 2024). "RAD52, an important protein for homologous recombination, was found to have an important role in genomic stability maintenance and cancer suppression in mammalian cells." (PMID 37270714, 2024). "These pieces of evidence further support the idea that RAD52 inhibition is a promising approach to targeting specific types of cancer (depending on RAD52 expression level) and pursuing precision and personalized medicine." (PMID 36980703, 2023). "RAD52 mediates many of these alternative pathways, and while not normally essential for cell survival, RAD52 is essential in cancer conditions where other DSB repair-related proteins are mutated." (PMID 36980703, 2023). "Overall, they reported different expression states of RAD52 depending on the cancer type but showed contradictory expression patterns." (PMID 36980703, 2023). "This review will describe the current knowledge of RAD52’s main structural and functional hallmarks and report its current involvement in cancer therapies." (PMID 36980703, 2023). "Further characterizations of the most promising compounds often involve cellular experiments focused on RAD52 molecular activity, especially in BRCA-deficient cancer cells." (PMID 36980703, 2023). "Researchers have devoted considerable effort to identifying and characterizing RAD52 inhibitors for synthetic lethality strategies in BRCA1/2-depleted cancers and in cells with drug-induced BRCA1/2 depletion." (PMID 36980703, 2023). "Inhibiting RAD52 induces synthetic lethality in many cancer cells with defective DNA repair-related proteins, such as BRCA1, BRCA2, PALB2, XAB3, and RAD51 paralogues (i.e., RAD51B, RAD51C, RAD51D, XRCC2, XRCC3)." (PMID 36980703, 2023). "Different studies have shown that there is a clear correlation between RAD52 misregulation and cancer." (PMID 36980703, 2023). "We found that RAD52 readily partitions into phase-separated RPA droplets in vitro, and that RAD52 enrichment at sites of ALT activation is reduced in cancer cells expressing phase-separation-impaired, phosphomimetic RPA2." (PMID 36894693, 2023). "Together with the optoDroplet and in vitro RPA phase separation data, these results support the notion that the propensity of RPA to form dynamic condensates promotes telomere clustering and facilitates RAD52-mediated telomere maintenance in ALT cancer cells." (PMID 36894693, 2023). "Collectively, our findings reveal a new role of RAD52 in protecting G4 integrity and provide insights for new cancer treatment strategies." (PMID 36470428, 2022). "Here we show that RAD52 and BRCA2-BRCA1-PALB2 co-mutations do occur in cancer cells but always in a heterozygous state." (PMID 36107942, 2022). "Based on the cause of cell death by DSB unrepair, cancer cells have a higher DSB burden, and hence the relationship between DSB and RAD52 can be exploited for cancer treatment." (PMID 34938740, 2021).
cancer (continued). "POLQ was revealed to be synthetic lethal with DNA repair genes frequently mutated in cancer (such as ATM, ATR, BRCA1/2, FANCD2, Ku70, RAD52, RAD51C, TP53BP1) and extensive efforts for the development of Polθ inhibitors are made by several companies." (PMID 34201502, 2021). "In a study of cancer cells containing an inactivated RECQL4 gene and upregulated RAD52, inhibition of RAD52 sensitized the cancer cells to ionizing radiation." (PMID 34887904, 2021). "Mammalian RAD52 participates in break-induced replication (BIR) repair of collapsed DNA replication forks in cancer cells." (PMID 34201502, 2021). "In conclusion, our data indicate that curcumin, which has RAD52 inhibitor activity, is a promising candidate for sensitizing BRCA2-deficient cells to DNA damage-based cancer therapies." (PMID 33922657, 2021). "Recent works have shown that because of its important role in various aspects of the DDR, RAD52 also has potential as a therapeutic target in the treatment of hereditary breast, ovarian, and some other cancers." (PMID 34887904, 2021). "Studies have demonstrated that inhibition of RAD52 gene function in BRCA2-deficient cancer causes synthetic lethality, suggesting a potential application of RAD52 in cancer-targeted therapy." (PMID 33995041, 2021). "Our results indicate that the simultaneous inhibition of RAD52-mediated DNA repair with the induction of DSBs appears to exaggerate the cytotoxicity of mitoxantrone and doxorubicin in BRCA1-deficient cancer cell lines." (PMID 33784323, 2021). "Therefore, BRCA1- and TP53BP1-deficient cancer cells may be eliminated by SSA/RAD52 inhibition." (PMID 33671579, 2021). "Overexpression of RAD51 or RAD52 rescued the XAB2 defects and XAB2 loss was synthetically lethal with RAD52 inhibition, providing potential perspectives in cancer therapy." (PMID 34500463, 2021). "Here, we will focus on the recent advancements in understanding RAD52’s role in various DNA repair pathways, and on the work that is underway to develop RAD52 inhibitors that can serve as cancer therapeutics." (PMID 34887904, 2021). "Second, we need to improve our understanding of the cellular circumstances beyond BRCAness under which targeting of RAD52 can lead to cancer cell death and when RAD52 inhibition can be combined with other inhibitors or DNA damaging chemotherapy." (PMID 32050645, 2020). "Cancer inactivating BRCA2 mutations are characterized by large tandem duplications and deletions which are typical for RAD52-mediated BIR and SSA repair mechanisms, contributing to rearrangements, fuelling genomic instability and oncogenic transformation." (PMID 31799622, 2020). "Thismakes RAD52 an appealing target for cancer therapy, as it will onlyhave key function in HR when BRCA1/2 are inactive: this will thereforehave a selective effect on cancer cells, without influencing healthcells." (PMID 33135887, 2020). "Its compensatory role in the resolution of DNA double-strand breaks has put RAD52 in the focus of synthetic lethal strategies, which is particularly relevant for cancer treatment." (PMID 32192055, 2020). "To take advantage of the RAD52 inhibition in cancer therapy we need to make multiple advances on several fronts." (PMID 32050645, 2020). "MiR-302 represses RAD52 transcripts in breast cancer cells, providing to radioresistance and allow cancer cells to survive." (PMID 32650508, 2020). "In this Special Issue, we would like to focus on the various functions of the RAD52 helicase-like protein and the current implications of such findings for cancer treatment." (PMID 32192055, 2020). "We investigated possible correlations between RAD52 expression and cancer survival and response to preoperative radiotherapy." (PMID 32143539, 2020). "Because replication stress is so prominent in cancer, it is possible that treatment with RAD52 inhibitors will have therapeutic effect even in HDR‐proficient tumor cells." (PMID 32175645, 2020).